RPLP0P6 (ribosomal protein lateral stalk subunit P0 pseudogene 6)
Description:
Ribosomal protein P0 is the functional equivalent of E.coli protein L10.
Synonyms: RPLP0_2_209
Gene: Processed pseudogene on chromosome 2 (38,481,851 to 38,482,804, forward strand). Ensembl gene ENSG00000213553.
Diseases named in the same sentence as RPLP0P6 in open-access papers:
RPLP0P6 is named in the same sentence as 1 disease in open-access papers, as found by Europe PMC text mining. Sharing a sentence is not in itself a finding about the gene and the disease. The quoted sentences say what the papers report.
tumor (1 paper, 2023). "However, there is evidence that EEF1A1P5 gene transcripts and the RPLP0P6 protein are present in exosomes of various tumor cell lines." (PMID 37298233, 2023).